AURKB (aurora kinase B)
Diseases named in the same sentence as AURKB in open-access papers (continued):
Sharing a sentence is not in itself a finding about the gene and the disease.
cancer (continued). "Interestingly, KSHV latently infected tumor cells showed serine protease-N terminus cleavage of AURKB, an N'-cleaved form of AURKB protein also shared in malignant tumor cells induced by other oncoviruses including EBV and HPV." (PMID 33154944, 2020). "AZD 1152, another selective inhibitor of AURKB, was also able to inhibit the growth of different human cancer xenografts including that of the lung, via suppression of histone H3 phosphorylation, accumulation of 4N DNA in cells and increased proportion of polyploid cells." (PMID 33202573, 2020). "Both proteins AURKB and BUB1 are linked in literature with the poor prognosis of different cancers." (PMID 32564237, 2020). "Furthermore, AURKB is known to induce proliferation and survival in cancer cells during tumor development." (PMID 32761869, 2020). "Our studies suggest that targeting contextual non-directional cell motility through dual inhibition of PLK4 and AURKB might be an important therapeutic goal in the cancer clinic." (PMID 31142743, 2019). "It is tempting to speculate that the elevated expression of RecQL4 confers survival advantage to cancer cells by protecting them from mitotic irregularities through upregulation of AURKB." (PMID 30206236, 2018). "It is likely that hTERT activation leads to RecQL4 upregulation, which in turn can protect the telomere stability in cancer cells both by its unwinding and DNA repair activities, and meanwhile, both RecQL4 and AURKB work in a concerted manner to achieve the telomeric stability in cancer cells." (PMID 30206236, 2018). "AURKC may promote tumor development in view of overlapping and complementary function with AURKB, as well as gene amplification and overexpression in cancers though the mechanism is still in dispute." (PMID 28147341, 2017). "Additionally, it has been shown that AURKB conferred cancer cell resistance to tumor necrosis factor-related apoptosis-inducing ligand (TRAIL)-induced apoptosis via phosphorylating survivin." (PMID 28147341, 2017). "Further studies are needed to clarify the role of AURKB rs1059476G>A in cancer." (PMID 28977903, 2017). "Representative Cyclin D1 target genes were chromosome segregation factors such as AURKB and CENPM that have previously been identified as targets of Cyclin D1 in mouse embryonic fibroblasts and have been implicated in chromosome instability in cancers." (PMID 26883361, 2016). "CDCA8 and aurora kinase B (AURKB) are overexpressed in tumor cells and selective suppression of the CDCA8-AURKB pathway may be a promising therapeutic strategy in the treatment of cancer." (PMID 26096802, 2015). "In addition, pan-aurora kinase inhibitors, VX-680 and CCT137690 which also target AURKB, were reported to sensitize cancer cells with high expression of MYC and MYCN." (PMID 26497213, 2015). "Aberrant activity of cell cycle kinases, including aurora kinase B (AURKB) and cyclin-dependent kinase 1 (CDK1), might lead to disrupted mitotic checkpoints, causing aneuploidies and uncontrolled proliferation, which are critical hallmarks of cancers." (PMID 41357898, 2025). "Our study reveals that AURKB may be a potential biomarker for pan‐cancer and KIRC." (PMID 38898693, 2024). "However, AURKB is a potentially poor prognostic marker for several cancers related to aneuploidy." (PMID 38396874, 2024). "Moreover, DDR is regulated by AURKB in multiple types of cancers." (PMID 38515112, 2024). "Interestingly, AURKB inhibitors are currently being investigated as anti-cancer drugs." (PMID 37459363, 2023).
cancer (continued). "According to several previous studies, changes in the expression of AURKB may lead to the failure of cell mitosis, resulting in the production of polyploids, which is also considered a prerequisite for the occurrence of malignant tumors." (PMID 35088239, 2022). "Combination therapy of AURKB inhibition along with other small molecule inhibitors with activity against tumors or traditional chemotherapy agents is the need of the hour and should be pursued rapidly to achieve additional armamentarium in the fight against cancers." (PMID 33915740, 2021). "Therefore, AURKB is considered as a potential therapeutic target in cancer." (PMID 32811973, 2021). "Additionally, genes that are critical to cancer growth and metastasis, such as AURKB, PCNA, fascin, and FILIP1L, may also play a role in the cooperative anti-tumor activity of vitamin C and buparlisib." (PMID 33664847, 2021). "Previous studies showed that an AURKB inhibitor could help overcome drug resistance in cancer." (PMID 32863956, 2020). "All of these proteins are over-expressed in different types of cancer (breast, prostate, lung, gastric, etc) and correspond, for example, to the insulin-like growth factor 1 receptor, the macrophage-stimulating protein receptor and the aurora kinase B, among others." (PMID 31261733, 2019). "Also, their phenotypic anti-cancer impact may, in part, be a consequence of the inhibition of AURKs, especially AURKB." (PMID 31035676, 2019). "Several clinical inhibitors of AURKB, such as barasertib (AZD1152), have been evaluated for their ability to disrupt mitotic progression and induce apoptosis in cancer cells." (PMID 41357898, 2025). "Let-7b-5p expression was significantly reduced in all parental BC cancer cells and Dox-resistant BC cells compared to MCF-10A cells (P < 0.05), while AURKB expression was increased (P < 0.05)." (PMID 39787178, 2025). "Drugs targeting AURKB, BCL-2, or EZH2 are currently in various stages of clinical development and have shown promising results for treating certain cancers." (PMID 38961535, 2024). "Findings from the CPTAC database indicated that cancer tissues of BRCA, HNSC, LIHC, LUAD, PAAD and UCEC exhibited notably elevated AURKB protein expression in comparison to normal tissues." (PMID 38898693, 2024). "However, the upstream regulatory mechanism of AURKB expression in cancers remains unclear." (PMID 38233848, 2024). "The findings of this study indicate a positive correlation between the expression of AURKB and the level of CD4+ Th2 cells in various types of cancers, with the exception of TGCT." (PMID 38898693, 2024). "Compound 15 degrades AURKA with low DC50 value of 2.05 nM, which is 77-fold and 21-fold more selective toward AURKB and TTK and has an EC50 value of 39 nM against cancer MV4-11 cells." (PMID 39539259, 2024). "These included CALB1, AURKB, SEPT14, and the histone-coding gene HIST1H1B and downregulated ADH1B and C7 in 11 cancer types." (PMID 38763334, 2024). "Many proteins regulating mitosis have emerged as targets for cancer therapy, including the kinesin spindle protein (KSP) and Aurora kinase B (AurB)." (PMID 38893134, 2024). "As observed in studies with cancer cells, AURKA protein interacts more strongly with CCT137690 than AURKB, which is also the case for the tick proteins." (PMID 39542861, 2024). "SCL/TAL1 interrupting locus (STIL) promotes proliferation, invasion, and cancer progression by regulating the expression of CDK1, CCNB2, CDC20, CCNA2, BUB1, and AURKB." (PMID 36661515, 2023). "Aurora Kinase B (AURKB) is a central regulator of chromosome separation and cytokinesis and is abnormally expressed in a variety of cancer cells." (PMID 37318676, 2023).
cancer (continued). "In contrast to other cell cycle checkpoints, the SAC is an essential device for survival in all metazoan cells, including cancer cells; and agents against TTK, APC/C or AURKB have been developed." (PMID 37443114, 2023). "Overall, the data highlight KDM5D/AURKB axis in which KDM5D modulates AURKB expression generates platinum-tolerant persister cells, enhances cancer stemness potential, activates the diapause-like state, and alters platinum sensitivity in HNSCC." (PMID 36982384, 2023). "In contrast, expression of AURKB and TOP2A (cell cycle genes) in cancer cells was significantly downregulated after pembrolizumab treatment, indicating a reduction in cancer-cell proliferation." (PMID 36973261, 2023). "Aurora kinase A (AURKA) and Aurora kinase B (AURKA), which their overexpression is highly related to cancer emergence, have been found to play a crucial role in cell proliferation and division." (PMID 37231064, 2023). "To date, a lot of APC substrates involved in cell cycle regulation have been demonstrated to be overexpressed in several cancer types, including CDC20, the Aurora A and B kinases (AURKA and AURKB, respectively) and Forkhead box M1 (FOXM1)." (PMID 37447165, 2023). "Molecular dynamics simulations were conducted on three AURKA and AURKB systems bound by three inhibitors (HPM, MPY, and VX6) to gain insights into their binding selectivity for anti-cancer drug development." (PMID 38113210, 2023). "BRD4 has received considerable attention as a cancer therapy target because several cancers depend on BRD4-mediated c-myc, fos, and aurora kinase B expression." (PMID 36991452, 2023). "Based on the statistical analyses of the PPI network of upregulated genes, AURKA, AURKB, TTK, MELK, and KIF20A were also involved in module 1, indicating their importance both in primary tumorigenesis and cancer progression." (PMID 37231064, 2023). "One report revealed that aurora kinase B (AURKB) phosphorylates CDCA8 in vitro, and a simultaneous co‐transactivation of CDCA8 and AURKB is typically seen in multiple cancers." (PMID 36855818, 2023). "Survivin, together with INCENP, borealin, and AURKB to form CPC, has been reported to be overexpressed in many cancers and enable chemotherapy resistance." (PMID 35659274, 2022). "These drug molecules also showed significant binding performance with some cancer-related PTM-sites (phosphorylation, succinylation, and ubiquitination) of top-ranked four key proteins (EGFR, AURKB, BIRC5, and TOP2A)." (PMID 36567949, 2022). "AURKB is a key kinase of the chromosomal passenger complex (CPC), which is essential for proliferation of cancer cells." (PMID 35853811, 2022). "Finally, we investigated whether LDR-IR affected the sensitivity of anti-cancer drugs targeting the cell cycle or Aurora kinase B, and interestingly found that pre-treatment with LDR-IR significantly reduced the sensitivity to paclitaxel or barasertib in TIG-3 but not in A549 cells." (PMID 35159310, 2022). "Then, we validated them by molecular docking analysis with some cancer-related PTM-sites (phosphorylation, succinylation, and ubiquitination) of the four top-ranked key proteins EGFR, AURKB, BIRC5, and TOP2A." (PMID 36567949, 2022). "Cancer cells with deregulated MYC are specifically characterized by a mitotic vulnerability, and AURKB was demonstrated to be synthetically lethal with MYC." (PMID 35439169, 2022). "A recent study has demonstrated that oncogenes found in many cancer entities, such as MYC, aurora kinase B (AURKB) and HRAS, trigger hyperactivation of ESCRT and ceramide pathways, as well as the inhibition of lysosome genes causing abundant sEV secretion." (PMID 34503190, 2021). "Inhibition of AURKA or AURKB triggers transient mitotic arrest, polyploidization, and apoptosis of MYC expressing cancer, phenotypes reminiscent of those observed here for diMF." (PMID 33760847, 2021).
cancer (continued). "Our analysis revealed that the expression patterns of AURKB, CCNB1, PLK1, and USP7 were all higher in tumor tissues than in normal tissues, although their basal levels were different in each cancer." (PMID 33207738, 2020). "More importantly, deregulation of genes in this module including PLK4, AURKB, DAAM1 and DAAM2 are correlated with aggressive forms of human cancer." (PMID 31142743, 2019). "AURKB, HOXB7, KYNU, and LCP1 are strongly upregulated in CESC, with the first two also upregulated in multiple other cancer types." (PMID 30918060, 2019). "For example, we observe that PLK1, CCNB1/2, CCNA2, AURKB and BUB1B are shared across 6–9 cancer types and physically interact with several deregulated neighbouring genes in our activated modules." (PMID 31396397, 2019). "Several other proteins such as AURKA, AURKB, CHEK1, BIRC5, CDC25B decreases their local PageRanks in cancer which means they become more controlled." (PMID 29370181, 2018). "The gene expression levels of cyclin B1 (CCNB1), cyclin B2 (CCNB2), Aurora A (AURKA), Aurora B (AURKB), and PLK-1 (PLK1) were increased from stages 1 to 4; however, the genes for D-type cyclins were expressed in a stable manner across the cancer stages." (PMID 30235818, 2018). "Based on its increasing importance as a cancer-related, druggable molecule and its differential expression between WHO°III and °I (p < 0.01), we additionally included AURKB in our analysis." (PMID 26894859, 2016). "Since our data revealed that PRMT1-mediated INCENP methylation is critical for the activation of AURKB, we then examined the effect of PRMT1 knockdown on the cell division of cancer cells." (PMID 26460953, 2015). "Because these cells also express AURKB, studying the functions of AURKC in cancer cell division poses the same specficitiy difficulties as in oocytes." (PMID 24586209, 2014). "Aurora kinase B (AURKB) is a mitotic checkpoint kinase that mediates chromosome segregation and is overexpressed in a variety of cancers including lung, colorectal, and prostate." (PMID 24324792, 2013). "We analysed cdc14A, that regulates centrosome separation and activates the anaphase promoting complex cdh1/APC, Ndc80/Hec1 (Highly Expressed in Cancer;) a component of APC and Aurora Kinase B, a key regulator of chromosome segregation." (PMID 21187932, 2010). "According to these results, the first circuit by which PLK1 may participate in a genomic instability event in cancer is through deregulation of the chromosomal passenger complex [CPC] and the Aurora kinase B [AURKB] regulatory pathway." (PMID 40430225, 2025). "AURKB inhibitors (AURKBi) have been investigated in a broad range of cancers, but none have yet been approved for clinical use." (PMID 39779678, 2025). "The data presented here show that, in addition to FOXM1, targeting AURKB and PLK1 may curb the increased cell proliferative activity of cancer cells." (PMID 40149290, 2025). "Similar to other USP29 substrates c-MYC, HIF1α and Snail1, AURKB deregulation often occurs in cancers, implying that USP29 may become a potential target for cancer treatment." (PMID 38233848, 2024). "Unsurprisingly, AURKB is one of the genes in the CIN70 gene signature; CIN70 genes are genes whose overexpression potently drives chromosomal instability and functional aneuploidy in multiple cancer types." (PMID 39335162, 2024). "Our analyses of TCGA and GTex tumor data and matched normal samples from TCGA and GTex datasets using the Gene Expression Profiling Interactive Analysis (GEPIA) tool showed that KIFC1, AURKB, BIRC5, and CDCA8 are all significantly overexpressed in many different cancer types." (PMID 39335162, 2024).
cancer (continued). "We analyzed RNA sequencing expression data of 9736 tumors and 8587 normal samples from The Cancer Genome Atlas (TCGA) and the Genotype-Tissue Expression (GTEx) projects for the expression profiles of centrosome clustering proteins KIFC1, AURKB, BIRC5, and CDCA8." (PMID 39335162, 2024). "However, there is a lack of mechanistic studies revealing the potential interactions and biofunctions between AURKB and MAD2L2 in cancer biology in BC cells." (PMID 38515112, 2024). "Both AURKB and MAD2L2 are overexpressed in various human cancers and have synergistic oncogenic effects; therefore, they are regarded as emerging therapeutic targets for cancer." (PMID 38515112, 2024). "Several studies have reported the coactivity of AURKB and MAD2L2 in cancer cells." (PMID 38515112, 2024). "CDCA8, AURKB and PLK1 were also three hub ICPs in multiple kinds of cancers." (PMID 37770497, 2023). "AURKB is found overexpressed in many cancer types and is a negative prognostic factor in NSCLC and hepatocellular carcinoma amongst other tumors." (PMID 36387232, 2022). "Aurora kinase B (AURKB) is a type of functional kinase with primary functions of participating in cell mitosis, which has been identified to be involved in the occurrence and development of malignant tumors strongly." (PMID 35088239, 2022). "The cancer target PDB ID 1RY0 (AKR1C3) showed the highest interactions with the majority of the NCs, followed by 1HFQ (DHFR), 3ZGC (NFE2L2), 4AF3 (AURKB), 4K33 (FGFR3), 5P21 (HRAS), 2I0V (CSF1R), and 3ZIM (PIK3CA) protein targets and least interaction was found with the 1M9Z (TGFBR2) protein." (PMID 36387366, 2022). "Moreover, the extent to which EVs are elevated in cancer depends on the amplified genes in that cancer; for example, MYC and AURKB promote the release of some of the highest EV numbers." (PMID 36139610, 2022). "As shown in the heatmaps, the hsa_circ_0001495, miR-125b-5p, and GPM6A were down-regulated in cancer tissues compared to their paired para-carcinomal tissues of HCC, whereas hsa_circ_0000688, miR-106b-5p, and four mRNAs (UNKL, GPRIN1, SMYD5, AURKB) were up-regulated." (PMID 35002514, 2022). "In addition, research has shown that three members of the Aurora kinase family (AURKA, AURKB, and AURKC) play an important role in cancer cell migration and tumor progression." (PMID 36482411, 2022). "In cancer cells, the subcellular localization of AURKC is the same as that of AURKB suggesting that they could have similar functions." (PMID 34465813, 2021). "Drugs with targets such as EGFR, ERBB2, MTOR, PARP2, AURKB, MAP2K1 and PLK1 share more similar profiles, which indicates that the inhibition of these targets has specific effects on the in vitro viability and proliferation of cancer cells." (PMID 33795761, 2021). "However, it is clear that the impact of HDAC inhibition on AURKA, AURKB, and AURKC expression is significant and should be used as an additive strategy for inducing cell cycle arrest and cell death in cancers where the AURK family of proteins are elevated." (PMID 34066975, 2021). "Many reports have elaborated on the role of AURKB in neoplasia and cancer; however, no previous study has shown its role during organ development." (PMID 33462217, 2021). "Indeed, the chemical inhibitors of the kinetochore genes AURKB, TTK, and NDC80 have been proven effective in cancer therapy in preclinical studies." (PMID 33803928, 2021). "In fact, inhibition of AURKB has been found to lead to polyploidy in vitro in both cancer and non-cancer cells." (PMID 31035676, 2019).